MMP8 (matrix metallopeptidase 8)
Diseases named in the same sentence as MMP8 in open-access papers (continued):
Sharing a sentence is not in itself a finding about the gene and the disease.
periodontitis (continued). "The concentration of MMP-8 levels following treatment significantly decreased 6 months post-surgical intervention in both smokers and non-smokers with periodontitis." (PMID 36360962, 2022). "In addition, matrix metalloproteinase-8 (MMP-8), matrix metalloproteinase-9 (MMP-9), and matrix metalloproteinase-13 (MMP-13) are present in higher levels in the saliva of individuals with periodontitis than in the saliva of healthy individuals." (PMID 35048079, 2021). "Therefore, we selected these four marker candidates (IL-1β, MMP-8, ICTP, and Pg) and evaluated their efficiency for diagnosing gingivitis and periodontitis." (PMID 34001101, 2021). "MMP-3 (stromelysin-1) is a notable proteolytic enzyme among the other MMP types due to its central role in activating the latent MMP types such as MMP-7, MMP-8, MMP-9, and MMP-13, and it has been claimed that MMP-3 has a pivotal function in the initiation of collagen disintegration in periodontitis." (PMID 34684209, 2021). "In the same study, clinical periodontal parameters were positively correlated with the expression of both MMPs in GCF, and pregnant women with periodontitis stage III and IV showed increased concentrations of MMP-8 when compared with pregnancies with periodontitis stage I." (PMID 34769262, 2021). "We demonstrated that IL-1β and ICTP in combination yielded a similar AUC value (0.917) to differentiate periodontitis subjects from healthy subjects when compared to the combination of IL-1β, MMP-8, and Pg (0.920), indicating that IL-1β and ICTP are more effective for predicting periodontitis." (PMID 34001101, 2021). "In the following years, more studies confirmed the inhibitory effects of proanthocyanidins and its galloylated monomers on production and/or activity of matrix metalloproteinases MMPs (MMP-1, MMP-2, MMP-3, MMP-7, MMP-8, MMP-9, and MMP-13) involved in periodontitis." (PMID 33467650, 2021). "MMP-8 is responsible for the beginning of collagen degradation, hence, measuring GCF MMP-8 levels can offer a site-specific diagnosis of periodontal disease, longitudinal monitoring of periodontitis and assessment of treatment outcomes." (PMID 33952216, 2021). "The plotted ROC curves showed a good predictor value of the MMP-9/TIMP-1 ratio, (MMP-8 + MMP-9)/TIMP-1 ratio, and HGF (as top three), followed by the MMP-9, MMP-2, MMP-8 + MMP-9 sum and the MMP-8/TIMP-1 ratio, for differentiation of periodontitis versus health conditions (AUC ≥ 0.95)." (PMID 33742017, 2021). "Our results showed that MMP-8 was not significantly elevated in the periodontitis group compared to the gingivitis group, and ICTP was not significantly elevated in the gingivitis group compared to the healthy group." (PMID 34001101, 2021). "The plotted ROC curves showed a good predictor value for the MMP-9/TIMP-1 ratio, the (MMP-8 + MMP-9)/TIMP-1 ratio and the MMP-8 + MMP-9 sum (as top three), followed by the MMP-8/TIMP-1 ratio, HGF, MMP-2, and OPG for differentiation of periodontitis versus gingivitis conditions (AUC ≥ 0.85)." (PMID 33742017, 2021). "The pooled standardized mean difference of IL-1β and MMP-8 was −1.04 and 35.90, respectively, but the differences between periodontitis patients and healthy controls were not significant." (PMID 33383828, 2020). "MMP-8 (also known as type neutrophil collagenase or collagenase 2) has substrate specificity for type I collagen, accounting for periodontal extracellular matrix; thus, attention has been paid to MMP-8 in periodontitis." (PMID 33066545, 2020). "Instead, some of them detect the total MMP-8, which is not able to detect periodontal breakdown or progression of periodontitis." (PMID 31979091, 2020). "Pathologically-elevated levels of MMP-8 have been reported in periodontal disease in comparison to healthy patients’ sites, which was in accordance with this work, where MMP-8 was able to identify periodontitis sites and discriminate according to its severity." (PMID 33143325, 2020).
periodontitis (continued). "Furthermore, recent proteomic investigation also confirmed that MMP8 along with other cytokines (interleukin-1b–IL-1b, RANK/RANKL/OPG) were overexpressed in periodontitis." (PMID 32646009, 2020). "The aim of this study was to evaluate the effects of probiotics on the periodontal parameters and MMP-8 levels in GCF of chronic periodontitis patients before and after nonsurgical periodontal therapy with and without the adjunctive use of probiotics." (PMID 32438428, 2020). "ROC analysis revealed that both ELISA and sensor analysis for salivary MMP-8 provided similar sensitivity and specificity in terms of distinguishing MMP-8 levels in healthy individuals from those in both gingivitis patients and periodontitis patients." (PMID 31363141, 2019). "We also tested the ability of the biosensor assay to measure changes in MMP-8 6 months after the commencement of non-surgical treatment for periodontitis." (PMID 31363141, 2019). "Increased levels of especially active MMP-8 (aMMP-8), but not latent, inactive proform, have been found in periodontitis- and peri-implantitis-affected oral fluids (saliva, mouth rinse, gingival crevicular fluid (GCF), and peri-implant sulcular fluid (PISF))." (PMID 30154936, 2018). "A recent study showed that MMP-8 levels in patients that were both smokers and non-smokers with chronic periodontitis have significantly reduced after periodontal therapy SRP." (PMID 28403357, 2017). "Levels of MMP-8 are elevated in gingival tissue, GCF and saliva in periodontitis patients." (PMID 29163477, 2017). "In line with these notions, increased periodontal expression of interleukin (IL)-6 and MMP-8 across patients with neither periodontitis nor T2DM, patients with periodontitis alone and patients with both diseases was reported by our group." (PMID 26581717, 2015). "Finally, our diverse analyses allowed us to provide potential thresholds to discriminate periodontitis (i.e., IL-1ß: 24–28 pg/mL; IL-6: 5.11–5.5 pg/mL; MIP-1α: 3.28–5 pg/mL, and MMP-8: 140–165.9 ng/mL)." (PMID 26347856, 2015). "The objective of this study was to investigate the levels and associations of salivary MMP-8, -9, MPO and tissue inhibitors of metalloproteinase (TIMP)-1 in myocardial infarction (MI) patients and controls with or without periodontitis." (PMID 26132583, 2015). "This study identified some 20 proteins which were differentially expressed in periodontitis saliva and most, including MMP-8, MMP-9, α2-macroglobulin, and complement C3, have previously been identified as potential biomarkers in conventional analysis of periodontitis saliva." (PMID 24944840, 2014). "Salivary MMP-8 (but not MMP-9) levels were found to be reduced after nonsurgical treatment for periodontitis in 33 patients but, interestingly, not if adjunctive doxycycline treatment was included." (PMID 24944840, 2014). "In addition, other authors have evaluated the influence of diabetes in MMPs expression, demonstrating higher levels of MMP-8 and MMP-9 in periodontal tissue of diabetic patients with periodontitis." (PMID 22611374, 2012). "Although some research suggests that active MMP-8 (aMMP-8) may more effectively distinguish between healthy sites and those affected by periodontitis, MMP-8 has been found to differentiate between mild and severe periodontitis more accurately in certain cases." (PMID 40045958, 2025). "However, in periodontitis, their persistent activation and accumulation lead to the release of destructive enzymes such as MMP-8 and ROS, which damage periodontal tissues, rather than protect periodontal tissues." (PMID 41154468, 2025). "Salivary and plasma levels of IL-1β, IL-6, and TNF-α increase with periodontal disease severity, and plasma MMP-8 and MMP-9 levels decrease after non-surgical periodontal treatment events, supporting the theory of periodontitis causing increased systemic inflammation." (PMID 38672972, 2024).
periodontitis (continued). "Also in patients with periodontitis without diabetes, the level of salivary MMP‐8 is significantly higher than healthy people." (PMID 38433295, 2024). "Numerous oral biomarkers have been investigated in relation to periodontitis, and several studies have found elevated levels of aMMP-8, but not total/latent MMP-8, to differentiate periodontitis from both gingivitis and healthy periodontium, and to precede future tissue destruction." (PMID 39767238, 2024). "However, it should be noted that a single study indicates that the determination of MMP-8 concentration is not suitable for differentiating the stages of periodontitis." (PMID 38473967, 2024). "However, it should be noted that a single study indicates that the determination of MMP-8 concentrations is not suitable for differentiating aggressive periodontitis from chronic periodontitis." (PMID 38473967, 2024). "Therefore, it is an aMMP-8 and not a total MMP-8, which reflects clinically active and progressive periodontitis in oral fluids." (PMID 38786309, 2024). "In particular, we hypothesized that the GCF levels of RANKL, OPG, IL-6, IL-17A, and MMP-8 do not change during this orthodontic treatment and are lower than those detected during periodontitis." (PMID 36902236, 2023). "In addition, microbiomes from patients with periodontitis increased IL-6 and MMP8 secretion in 25 mM glucose but not in 5 mM glucose." (PMID 37240180, 2023). "Interestingly, results showed an up-regulation of colony-stimulating factor-1 (CSF-1), S100A8/A9, S100A12, interleukin (IL)-1β, matrix metalloproteinase (MMP)-8, and hepatocyte growth factor (HGF), in patients with periodontitis with a statistical significance of p<0.001." (PMID 37224160, 2023). "The results of this study also showed a positive correlation between MMP-1, MMP-8, TIMP-1 levels, and miR-1246 levels in the chronic periodontitis group, suggesting that increased miR-1246 expression may be associated with the destruction of periodontal tissues by proteases in chronic periodontitis." (PMID 35942384, 2022). "Polymorphisms of S100A9 or MMP8 did not associate with any periodontal parameters, whereas polymorphisms in CFH gene as well as saliva TCC concentrations were associated with clinical and radiographic signs of periodontitis." (PMID 35315933, 2022). "Therefore, this review was designed to answer a focused question regarding whether GCF MMP-8 level at baseline can be used to predict site-specific outcome of NSPT (manual, ultrasonic, or both) in patients with periodontitis." (PMID 35270821, 2022). "Furthermore, they observed, that compared to periodontitis, MMP‐8 is not activated, that is, converted to active forms and related fragmented low molecular size species throughout the course of gingival inflammation induction and resolution." (PMID 35676762, 2022). "Studies have been carried out on salivary MMP-8 and crevicular MMP-2, which were known to serve as biomarkers of periodontal disease; however, there is a dearth of literature on how type-II diabetes mellitus (type-II DM) influences the levels of MMP-9 in chronic periodontitis patients." (PMID 35408573, 2022). "Previous reports indicated that periodontal microbial infection enhances MMP‐8 gene and protein expression from HGFs and PDL cells and that the amount of MMP‐8 in the gingival crevicular fluid, gingival tissue, and PDL cells significantly increased in patients with chronic periodontitis." (PMID 35384365, 2022). "In the second place, the (t) MMP-8 crude model achieved a sensitivity of 60% and a specificity of 82% (at a cut-off point of 70.62 ng/mL), while the (a) MMP8-adjusted model was 63% sensitive and a 79% specific in discriminating periodontitis severity, with a cut-off point of 360.38 ng/mL." (PMID 34441437, 2021).
periodontitis (continued). "Sorsa’s study and others have demonstrated that total MMP-8 may not be able to effectively detect periodontal breakdown or progression of periodontitis and they concluded that, instead of total MMP-8, active MMP-8 (aMMP-8) levels truly reflect a proinflammatory state of periodontal disease." (PMID 34001101, 2021). "Interestingly, LT recipients with more advanced periodontitis had the lowest levels of MMP-8, although the differences were non-significant." (PMID 33916950, 2021). "However, plasma IL-1β, tumour necrosis factor-alpha (TNF-α), and metalloproteinase 8 (MMP-8) levels were not altered significantly by the induction of periodontitis or propolis treatment." (PMID 34070497, 2021). "The report suggested that the MMP-8 mouth rinse test (based on a simple method to collect and sample GCF) might be a promising future adjunctive and preventive method in diagnosing, staging, and grading periodontitis." (PMID 33143325, 2020). "However, it is known that the total absence of MMP-8 results in extensive progression of periodontitis so that it appears that a physiological MMP-level contributes to the resolution of inflammation." (PMID 33391628, 2020). "Furthermore, MMP-8 levels were higher in patients diagnosed with chronic periodontitis and diabetic, but P. gingivalis did not affect much." (PMID 30305812, 2018). "Nonetheless, their elegant 24/7 tongue sensor assay is not MMP-specific for the main collagenolytic MMP, MMP-8, upregulated and activated in periodontitis- and peri-implantitis-affected periodontal and peri-implant tissue, gingiva and oral fluids, including saliva, GCF, PISF, and mouth rinse." (PMID 30154936, 2018). "In contrast, the total MMP-8 biomarker, which is detecting both inactive pro-/latent- and active species of MMP-8), had much larger variability in its levels than collagenolytic aMMP-8 and was not statistically significantly associated with grade of periodontitis among 150 Greek adult patients." (PMID 40136755, 2025). "Therefore, it is important not to synchronize the collagenolytic aMMP-8 with non-collagenolytic total, or latentpro-MMP-8 forms in periodontitis and peri-implant diagnostics, as tMMP-8 levels may reflect non-pathological states." (PMID 41300956, 2025). "Moreover, a recently published systematic review and meta-analysis showed that the level of this biomarker (MMP-8) is clinically most useful in the diagnosis of periodontitis, regardless of whether the patient is a smoker." (PMID 40558889, 2025). "In addition, (iii) determine aMMP-8 and total MMP-8 levels before and after non-antibiotic anti-infective scaling and root planing treatment in chronic periodontitis (CP) in relation to healthy controls (HC), using independent aMMP-8 immuno—and catalytic activity assays." (PMID 38786309, 2024). "The same author detected that the administration of sDMARDs and bDMARDS did not affect the levels of salivary MMP-8, an enzyme produced by neutrophils that degrades type I collagen in the periodontium and type II collagen in articular cartilage, representing a new biomarker in periodontitis." (PMID 38139057, 2023). "Furthermore, aMMP-8, but not latent/total MMP-8, levels could differentiate between periodontitis and gingivitis as well." (PMID 30305812, 2018). "Chlorhexidine, the most widely used adjuvant in the treatment of periodontitis, acts as a non-specific MMPI through chelation of calcium and zinc cations, inhibiting MMP-2, MMP-8, and MMP-9." (PMID 41002732, 2025). "In patients with periodontitis, salivary MMP-8 is activated and fragmented, and studies have shown that aMMP-8, rather than total MMP-8 levels, correlates strongly with connective tissue destruction." (PMID 39554809, 2024). "In contrast, periodontitis and its relation to coronary artery study (PAROKRANK) found elevated clinical signs of periodontal inflammation and myeloperoxidase and MMP-8 biomarkers in non-myocardial infarction patients." (PMID 38433948, 2024).
periodontitis (continued). "Previous studies have also found increased MMP-8 (and MMP-9) levels and less favorable healing process in the gingival tissues of patients with chronic periodontitis and diabetes compared with periodontitis patients without diabetes." (PMID 38001886, 2023). "They observed that western blot analysis could not detect active MMP‐8 (aMMP‐8) forms and species during the induction and resolution of gingival inflammation, which is an important finding to help us to understand the possible the mechanisms that convert marginal gingivitis to periodontitis." (PMID 35676762, 2022). "Unlike former results, we found that MMP-8 levels detected both by ELISA and IFMA were correlated, even when disaggregating the groups between periodontitis and healthy sites." (PMID 34441437, 2021). "This study evaluated the gene expression of IL-1ß, IL-6, TNF-α, MMP-1, MMP-2, MMP-8, MMP-9, TIMP-1, and TIMP-2 in the gingival tissue of individuals with periodontitis or peri-implantitis compared to individuals without periodontal or peri-implant disease." (PMID 33291232, 2020). "Repeatedly pathologically elevated levels of aMMP-8, but not total/latent MMP-8, in oral fluids (mouth rinse, saliva, GCF, and PISF) show the positive correlation with the clinical and radiological parameters of periodontitis and peri-implantitis." (PMID 30305812, 2018). "In serum, the MMP‐8, MMP‐9, and TIMP‐1 concentrations were slightly higher in the no‐periodontitis patients but the differences were not statistically significant." (PMID 29744196, 2017). "We investigated serum and saliva concentrations of matrix metalloproteinases, MMP‐8, MMP‐9, and MMP‐13, and their tissue inhibitor TIMP‐1, in a group of patients with and without periodontitis from Sweden." (PMID 29744196, 2017). "In saliva, MMP‐8, MMP‐9, and TIMP‐1 values were slightly higher in the periodontitis patients, but again, the differences between groups were not significant." (PMID 29744196, 2017). "In the present study, the levels of different pro-inflammatory and pro-destructive mediators common between periodontitis and orthodontics were quantified, and it was shown that the levels of the RANKL, OPG, IL-6, IL-17A, and MMP-8 do not vary during the 2 years of orthodontic treatment." (PMID 36902236, 2023). "More recently, MMP‐8 and MMP‐13 in saliva increased with periodontitis disease progression and decreased after its nonsurgical treatment (Ozcan, Saygun, Serdar, Bengi, & Kantarci, 2016), but the concentration ranges were mostly higher for MMP‐13 and much lower for MMP‐8, than here reported." (PMID 29744196, 2017). "Thus, the aim of this study was to analyse the MMP-8 levels, the key collagenase responsible for the destruction of periodontal tissues, in GCF from patients with varying severity of periodontitis and in PISF from patients with healthy implants and no signs of mucositis or peri-implantitis." (PMID 28757684, 2017).